INS (insulin)
Diseases named in the same sentence as INS in open-access papers (continued):
Sharing a sentence is not in itself a finding about the gene and the disease.
Insulin resistance (continued). "However, HOMA-IR and the secretion of insulin and C-peptide in treated mice behaved similarly to BTBR WT mice, suggesting lower insulin resistance after FMT." (PMID 35409202, 2022). "In non-pregnant women with PCOS, insulin resistance (IR) and compensatory hyperinsulinemia contribute to hyperandrogenic traits as insulin facilitates androgen secretion." (PMID 36733795, 2022). "Insulin resistance does not affect the MAPK pathway, but it selectively impairs PI3K-dependent insulin signaling, which contributes to the positive associations between insulin resistance and endothelial dysfunction." (PMID 36140374, 2022). "While most studies test for only one of either insulin sensitivity or responsiveness, herein we demonstrate a reduction in both with inhibition of p300/CBP activity, which correlates with the pathophysiology of human insulin resistance." (PMID 34813504, 2022). "The increase of insulin level results from insulin resistance, insulin which is not effectively used by tissues, secondary hyperinsulinemia, and, consequently, the increase of the serum glucose level and the development of carbohydrate disorders." (PMID 35054072, 2022). "Interestingly, we discovered two significant insulin-related pathways, “insulin secretion” (FDR = 0.0898) and “insulin resistance” (FDR = 0.111)." (PMID 35606885, 2022). "Moreover, a reduction of insulin resistance (measured as HOMA-IR) was observed after starch supplementation, driven by decreased fasting insulin levels." (PMID 36118764, 2022). "Unlike adipocytes, macrophages are insensitive to insulin and retain the ability to take up glucose upon insulin resistance." (PMID 36012516, 2022). "The term “insulin resistance” is a pathological condition when cells in the muscles, fat, and liver do not respond well to insulin and cannot easily take up glucose from the blood." (PMID 36249262, 2022). "In addition, there were significant associations between the identified gut microbes and several insulin resistance-related phenotypes (HOMA-IR, fasting insulin, and HbA1c)." (PMID 35585555, 2022). "Interestingly, in PsA patients serum C3 was the only variable to predict insulin resistance (evaluated with a surrogate measure named HOMA-IR) and whole-body insulin sensitivity in multivariate models." (PMID 35242041, 2022). "Parameters of glycosylated hemoglobin (HbA1c), fasting blood glucose (FBG), postprandial blood glucose (PBG), fasting serum insulin (FI), insulin resistance (expressed in terms of HOMA-IR), insulin dose (ID) received, serum insulin antibody (IA), and C-peptide (CP) were tested." (PMID 35334901, 2022). "Patients with PCOS and obesity had significantly higher insulin resistance on OGTT as defined by HOMA-IR (4.02 vs 1.79) and lower insulin sensitivity as defined by WBISI (2.00 vs 5.13) compared to the group without obesity (p < 0.001 for both HOMA-IR and WBISI)." (PMID 35842601, 2022). "We believe this work will help to broaden the definition of insulin resistance in the brain by asking whether this process is mediated by reduced IR sensitivity, decreased receptor density, and/or impaired BBB insulin transport." (PMID 36009470, 2022). "It is well known that any defect of insulin and its related signal transduction such as PI3K/AKT signaling pathway could lead to insulin resistance." (PMID 35281088, 2022). "Moreover, OGTT and ITT showed an impaired glucose tolerance as well as diminished insulin response in animals fed HFD diet as compared to LFD animals, demonstrating the induction of insulin resistance in HFD animals." (PMID 35053322, 2022). "Since hepatic lipid accumulation plays an important role in developing whole-body insulin resistance, the GCN2 inhibition-mediated alleviation of hepatic steatosis may also be responsible for the increased insulin sensitivity in T2D mice." (PMID 36009303, 2022).
Insulin resistance (continued). "SFFs could stimulate insulin secretion, activate AMPK-α, promote glucose transport, and inhibit insulin resistance, gluconeogenesis, and hepatic adipose accumulation." (PMID 35873798, 2022). "Insulin sensitization and improvement of insulin resistance are not only international research hotspots but also important strategies in the current treatment of type 2 diabetes and cardiovascular diseases." (PMID 35371260, 2022). "Increasing evidence suggests that brain insulin resistance can lead to endothelial dysfunction, BBB dysfunction, oxidative stress, chronic inflammation and arteriolosclerosis due to failure of cells to respond to insulin." (PMID 35992100, 2022). "On the other side, high-intensity PA induced an improvement in inflammatory biomarkers and insulin resistance, with a reduction in IL-6, TNFa, CRP, and resistin and an increase in adiponectin, thus indicating that exercise exerts anti-inflammatory and insulin-sensitising effects." (PMID 35679338, 2022). "Insulin resistance is a pathological condition in which the insulin does not sufficiently effect through the insulin receptors (IRs)." (PMID 35684149, 2022). "Since leucine upregulates mTORC1, subsequently inducing the suppression of insulin signal transduction by phosphorylation of insulin receptor substrate-1 (IRS-1), leucine supplementation might worsen insulin resistance." (PMID 36235570, 2022). "The homeostatic model assessment of insulin resistance (HOMA-IR) based on fasting serum glucose and insulin levels is recognized as a robust marker and is widely used in clinical practice instead of hyperinsulinemic-euglycemic clamp, which is the gold standard test for the measurement of IR." (PMID 36277749, 2022). "However, Arslanian and colleagues reported greater insulin resistance in adolescents than adults, despite similar levels of adiposity and glycemic control, and this could be a result of the more substantial effect obesity has on insulin sensitivity in youth compared to adults." (PMID 35684120, 2022). "DM is a complex multifactorial metabolic disorder characterized by hyperglycaemia and lack of insulin release or insulin resistance." (PMID 36438767, 2022). "We also did not measure the insulin and adiponectin levels, while the insulin resistance is the most common factor present in prediabetic and adiponectin signaling plays an important role in both prediabetes and newly diagnosed diabetic." (PMID 36536959, 2022). "Therefore, for clinical practice, the homeostatic model assessment for insulin resistance (HOMA-IR), Matsuda index and the quantitative insulin sensitivity check index (QUICKI) are frequently used in population screening." (PMID 36364954, 2022). "As this process is independent of insulin secretion, fructose consumption can encourage hepatic lipid buildup even in the presence of insulin resistance." (PMID 36110403, 2022). "Lack of microglial InsR resulted in increased plasma insulin levels and insulin resistance in obese female mice." (PMID 35328354, 2022). "However, it is imperative to point out that the proper diagnosis of insulin resistance would require performing glucose tolerance tests (GTT) and insulin tolerance tests (ITT)." (PMID 36500974, 2022). "Furthermore, mice fed a high fat diet containing lard had elevated insulin and HOMA-IR measurement of insulin resistance after 20 weeks compared to mice fed a plant-based high fat diet (soy and cotton oil) or a standard diet." (PMID 35433789, 2022). "Insulin resistance is defined as the lack of sensitivity of target tissues to insulin, even at high insulin concentrations." (PMID 35563135, 2022). "Permanent blocking of its insulin-dependent counterpart AKT activation may lead to metabolic inflexibility and insulin resistance in the long run and may be a direct consequence of statin-treatment." (PMID 35216514, 2022).
Insulin resistance (continued). "In particular, IL10-MSCs treated mice had a more decrease in insulin resistance compared with MSCs treated mice, similar to NCD mice, indicating IL10-MSCs could significantly improve insulin sensitivity in HFD mice, close to basal level." (PMID 35715850, 2022). "We have previously reported insulin resistance dependent decrease in serine phosphorylation of Akt1, Akt2 and Akt3 in neuronal cells.We next proceeded to test the effect of PHLPP1 silencing on Akt isoforms in neuronal insulin signaling and resistance." (PMID 36376971, 2022). "It is a common, chronic, costly, and metabolic disease and characterized by high levels of glucose in the blood, which results from lack of insulin (type 1 diabetes), or insufficient insulin and insulin resistance (type 2 diabetes)." (PMID 35427392, 2022). "Furthermore, insulin levels were significantly higher in T2DM mice compared to group B (P < 0.05), demonstrating the development of insulin resistance." (PMID 36618687, 2022). "Previous another study reported that DPP4i improve insulin resistance evaluated by glucose clamp test in American, but insulin secretion did not change." (PMID 35672759, 2022). "TRE has been shown to significantly lower fasting glucose levels, fasting insulin levels, and insulin resistance, while increasing insulin sensitivity, although this was not universally observed." (PMID 35053991, 2022). "In addition, the homeostatic model assessment for insulin resistance (HOMA-IR) index, calculated using fasting insulin and blood glucose, is also a widely used indicator in clinical research for general evaluations of IR and MetS." (PMID 35215377, 2022). "The similar plasma concentrations of cholesterol, glucose, and insulin in both genotypes indicate that an obesity-induced insulin-resistance was not (yet) present in the KO mice." (PMID 35915220, 2022). "GL was found to improve insulin resistance and downregulate RAGE expression spontaneously, suggesting that GL might improve insulin sensitivity via suppressing AGE-RAGE axis." (PMID 36232291, 2022). "Moreover, patients with a deleterious FA profile (higher FA Score values) have lower insulin sensitivity as determined by ISI index, and higher hepatic insulin resistance, as determined by the HIRI index." (PMID 34609622, 2022). "The well-known negative relationship between plasma adiponectin levels and insulin resistance suggests that adiponectin is the master regulator of insulin sensitivity and glucose homeostasis, possibly by activating AMPK." (PMID 36678531, 2022). "PRS interacted with energy intake, WSD, and smoking, indicating that the participants with high PRS generally failed to compensate for high insulin resistance by elevating insulin secretion, especially when having WSD and smoking." (PMID 35956399, 2022). "Moreover, the high levels of fasting plasma glucose (FBG), insulin (INS), HOMA-IR, and HOMA-IS were reversed by DBD, thereby improving the insulin resistance symptoms in GK rats." (PMID 36353458, 2022). "To evaluate insulin resistance, we determined OGTT, ITT, plasma insulin, and HOMA-IR." (PMID 36080407, 2022). "Some can probably increase their insulin secretion, but still not enough to compensate for the increase in insulin resistance." (PMID 35329371, 2022). "Indeed, Mondo A is also known to be a contributary factor to the development of insulin resistance through its increasing of the expression of thioredoxin interacting protein (TXNIP), impairment of insulin signaling, and increasing of lipogenesis." (PMID 35216280, 2022). "PCSK9 deficiency is associated with impaired glucose tolerance in mice, which appears to be the consequence of decreased insulin secretion from the pancreas rather than insulin resistance." (PMID 36558473, 2022).
Insulin resistance (continued). "Further analysis demonstrated that the anti-T2DM mechanisms of AGE were mainly related to suppressing inflammation, oxidative stress, endothelial dysfunction, dyslipidemia, insulin resistance, T2DM-related complications and enhancing immune response, and insulin secretion." (PMID 36120310, 2022). "Here, we report that patients with prostate cancer display higher fasting blood glucose levels and insulin resistance, without changes in insulin secretion." (PMID 36431238, 2022). "A plethora of evidence suggests AGEs/RAGE signaling pathway, NF-κB activation, inflammation, and ROS generation are directly related to the pathogenesis of insulin resistance by increased IRS-1serine phosphorylation and degradation, thus blocking the insulin signaling pathway." (PMID 35454131, 2022). "Studies have shown that when insulin resistance occurred in the hippocampus, the activity of PI3K/AKT, the main signaling molecule of the insulin signaling pathway, was decreased, which promoted the activation of GSK3β and phosphorylation of tau and promoted the pathological progression of AD." (PMID 36430894, 2022). "These relationships may be induced through the effects of high insulin levels possibly through IGF-1 R, insulin resistance, or hs-CRP." (PMID 36556950, 2022). "Fasting insulin and glycemia are both key molecules for insulin resistance and obesity-related chronic non-communicable diseases." (PMID 35326098, 2022). "The regulatory effect of MBPs for alleviating insulin resistance was studied by measuring body weight, fasting blood glucose (FBG) and serum insulin levels, C-Peptide levels, inflammatory and antioxidant factors, and histopathological observation of C57BL/6 mice." (PMID 35571892, 2022). "FT3 may also affect the expression of glucose-secreted insulin and an important protein of lipid metabolism; lower FT3 and FT4 levels can promote higher insulin resistance in tissues." (PMID 35784545, 2022). "Indeed, on one hand, the SPISE index displayed a strong cross-sectional correlation with dynamic OGTT-derived indicators of insulin sensitivity such as ISI, or with the widely used proxy of insulin resistance HOMA-IR." (PMID 34142364, 2022). "In addition, it was demonstrated that the surgical removal of the intra-abdominal fat improves IS in normal animals, but promotes insulin resistance in GHRKO mice, which are characterized by high insulin sensitivity and an extended lifespan." (PMID 36557289, 2022). "Lean women have reduced insulin sensitivity (insulin resistance) pre- and early pregnancy, but not in late pregnancy, as well as a reduction in first phase insulin release." (PMID 36520818, 2022). "Since insulin resistance is highly positively correlated with the progression of obesity, OGTT and ITT were completed for evaluating whether exercise could improve the insulin sensitivity of obese mice." (PMID 35782940, 2022). "For instance, Lactobacillus plantarum Ln4 (Ln4) can significantly reduce BG through stimulating glucose uptake in 3T3-L1 adipocytes, significantly decreasing insulin resistance index (HOMA-IR), and increasing oral glucose tolerance test (OGTT) and insulin response." (PMID 35685524, 2022). "did not assess the effect of insulin resistance and also 86% the data regarding insulin dose was missing." (PMID 35440685, 2022). "IL6 is an inflammatory factor, which can increase insulin resistance by upregulating the expression of cytokine signal pathway inhibitor 3, while blocking IL6 signal transduction can effectively improve glucose metabolism and insulin sensitivity." (PMID 36452059, 2022). "Nevertheless, multiple studies have shown that insulin hypersecretion precedes obesity and insulin resistance, which is not consistent with the notion of hyperinsulinemia being simply an adaptive response to insulin resistance." (PMID 36613492, 2022).
Insulin resistance (continued). "While Type 1 diabetes is the result of a reduced or absent insulin secretion, Type 2 diabetes is characterized by both insulin resistance and reduced insulin secretion in different proportions." (PMID 36615676, 2022). "Those who were obese in the GDM group had significantly higher serum insulin, insulin resistance (HOMA-IR), LDL-C, and CRP, than those who were not obese." (PMID 35817936, 2022). "In conclusion, in a cohort of BA men, neither insulin resistance, inflammatory cytokines nor adiponectin concentrations appear to fully account for their low insulin clearance." (PMID 34661756, 2022). "Indeed, hepatocyte-specific Ptpn11 knock-out mice displayed better glucose tolerance and insulin sensitivity, which translated into protection from HFD-induced insulin resistance and T2D." (PMID 36140242, 2022). "Currently, there is no universally accepted definition of insulin resistance because there is no standardized analytical method for measuring plasma insulin." (PMID 36419769, 2022). "T2D is characterized by insulin resistance, hyperglycemia, and the eventual lack of insulin secretion from β-cells." (PMID 35929791, 2022). "Another glycemic disorder is insulin resistance (IR) which muscles, fat, and liver cells do not respond to insulin effectively." (PMID 36704801, 2022). "Palmitate significantly reduced the acute insulin-mediated increase in GLUT4 plasma membrane levels, indicating insulin resistance (P+I: 135.2 ± 5.8% of control, p < 0.05); this response was restored in the presence of CA (CA+P+I: 194.4 ± 11.4% of control, p < 0.05)." (PMID 35011728, 2022). "However, it is unclear whether endothelial damage in penile arteries is related to whole-body insulin resistance, which is characterised by decreased responsiveness of the liver, adipose tissue and skeletal muscle to insulin, or is instead related to decreased endothelial insulin sensitivity." (PMID 34800144, 2022). "Not all obese children are insulin resistant, and insulin resistance can also occur in non-obese children." (PMID 34142364, 2022). "Based on reported role of TAZ/IRS1 axis in statin‐induced insulin resistance in skeletal muscle, we hypothesized that TAZ/IRS1 axis might be involved in the beneficial effect of GGPP on insulin signalling." (PMID 35961942, 2022). "Some representative features of metabolic syndrome in PCOS in both obese and non-obese patients include insulin resistance and high serum insulin levels, which are considered to interfere in ovulation and promote synthesis of ovarian testosterone." (PMID 35455702, 2022). "Several studies have shown that decreased insulin/PI3K/AKT signaling inhibits FOXO1 phosphorylation at the three sites (T24, S256, and S319), enhancing the subsequent nuclear translocation and activity of FOXO1, inducing insulin resistance." (PMID 35132380, 2022). "Along with this, insulin resistance and the resultant hyperinsulinemia are responsible for developing hypertension-related target organ damage (TOD) through the defects of the counter-regulatory effects of insulin." (PMID 35455055, 2022). "Current insulin therapies that are used to control insulin resistance do not offer much protection against comorbidities, such as DCM." (PMID 35757467, 2022). "In 18 population-based studies, six different methods were used to determine IR: homeostasis model assessment insulin resistance (HOMA-IR), fasted plasma insulin (FPI), the quantitative insulin sensitivity check index (QUICKI), the fasted glucose/insulin ratio (FGIR), HOMA2, and the McAuley index." (PMID 36465645, 2022). "Insulin resistance occurs when normal concentrations of insulin do not produce the adequate biological response of cellular glucose uptake." (PMID 36128718, 2022). "Patients with insulin resistance, obesity, and/or T2DM are exposed over the long term to high levels of pancreas-secreted insulin, which first passes through the liver (first passage insulin)." (PMID 35681699, 2022).